LCN2 (lipocalin 2)
Diseases named in the same sentence as LCN2 in open-access papers (continued):
Sharing a sentence is not in itself a finding about the gene and the disease.
infection (continued). "For example, lipocalin-2 or neutrophil gelatinase-associated lipocalin (NGAL), a protein secreted by neutrophils, macrophages and epithelia in response to infection binds to siderophores, such as enterobactin, and prevents bacterial iron acquisition by this route." (PMID 31824960, 2019). "In addition, Stat1-/-Gsdmd-/- and Stat1-/-Nlrp3-/- mice showed diminished fecal Lcn-2 levels upon gastrointestinal MNV infection." (PMID 31017981, 2019). "Thus, infection with E. coli O157:H7 elevated the levels of both Lcn2 mRNA and protein in the tissues and bloodstream of mice." (PMID 31781104, 2019). "LF82-infected eif2ak4−/− mice exhibited altered fecal microbiota composition at day 14 and 21 post-infection and increased fecal lipocalin-2 level at day 21 post-infection compared to other groups, indicating that intestinal inflammation developed after microbiota modification." (PMID 30120269, 2018). "It would be of great interest to establish whether the growth promoting effect of lipocalin-2 at the early stages of infection also applies to more virulent clinical M.tb strains." (PMID 30534124, 2018). "Only a few studies have investigated the in vivo role of lipocalin-2 in mycobacterial infection models and the focus has been on the role of lipocalin-2 at late time points following infection when the adaptive immune response is activated and mature granulomas have been formed." (PMID 30534124, 2018). "A decrease in the export of Ent in favor of release of linear DHBS molecules and use of alternate compensatory iron acquisition pathways could be a strategy for some K. pneumoniae strains to evade the bacteriostatic effects of Lcn2 during infection." (PMID 29669884, 2018). "We hypothesize that neutrophils deliver lipocalin-2 to mycobacteria-infected macrophages early in infection, thereby increasing the availability of intracellular iron and consequently facilitating mycobacterial growth." (PMID 30534124, 2018). "Together this supports our assumption that early in infection, when innate immunity dominates, M.tb is dependent on intracellular iron delivery from siderophores (both bacterial-produced and mammalian analogs) and lipocalin-2." (PMID 30534124, 2018). "Next, we analyzed the fecal microbiota composition in these mouse groups at the same time post-infection to investigate whether an altered microbiota composition could occur before or after the increase in lcn-2 level in LF82-infected eif2ak4−/− mice." (PMID 30120269, 2018). "However, lipocalin-2 is described as a potential biomarker of M.tb infection and its importance in infection models with other lung pathogens is well-described." (PMID 30534124, 2018). "However, all three strains release sufficient Ent to support robust growth in human serum, a matrix relevant to human infection, and that growth is inhibited by Lcn2." (PMID 29669884, 2018). "Lipocalin-2 levels in the KO/WT mice were comparable to uninfected mice at all time points, illustrating that there is no major contribution of lipocalin-2 from the myeloid population the first 14 days of infection." (PMID 30534124, 2018). "Interestingly, neutrophil number and activation at the site of infection were suppressed as assessed by fecal lipocalin-2, myeloperoxidase activity and neutrophil number despite more tissue damage by E. histolytica in antibiotic pre-treated mice." (PMID 28817707, 2017). "Furthermore, we demonstrated that lipocalin 2 (LCN2), which is released by neutrophils at sites of infection and inflammation is involved in HK2-driven autophagy pathway." (PMID 29285270, 2017). "Various repressors of apoptosis such as Ilf3, Zmym2, Satb1, Ccl21 and Scd were downregulated and expression levels of inducers of apoptosis such as Daxx, Oas1, Lcn2 and Gng2 were upregulated with V3000 infection at 24 h pi resulting in an overall activation of the apoptotic pathway." (PMID 28446152, 2017).
infection (continued). "Furthermore, IL-17A is an inducer of antimicrobial peptides including the β-defensins and lipocalin 2 (LCN2) that prevent infection at mucosal surfaces." (PMID 29048384, 2017). "Namely, 1-hour infection with E. coli might be insufficient for WT-derived TEPMs to express Lcn2, and inadequate Lcn2 expression in WT-derived TEPMs might result in the same level of phagocytosis and intracellular bacterial clearance as Lcn2KO-derived TEPMs." (PMID 27734904, 2016). "Therefore, we compared Lcn2 expression between WT- and IL-10KO-derived TEPMs after infection with E. coli." (PMID 27734904, 2016). "Although basal transcription of Ifnγ, S100A9 and Lcn2 was similar between mock-infected WT and mock-infected Ifnar1-/- mice, the transcription of Ifnγ and Lcn2 was significantly higher in the ceca of the Ifnar1-/- group, compared to the WT group, after infection with S. Typhimurium alone." (PMID 27149619, 2016). "Consistent with their resistance to infection, WT littermate controls, IL-17C-/- and IL-17RE-/- mice all exhibited similar gene profiles after inoculation, and representative genes such as Defb3 and Lcn2 were strongly induced in each cohort." (PMID 25849644, 2015). "During infection, LCN2 can intercept the ferric siderophore complex and inhibit bacterial growth." (PMID 26390966, 2015). "Lipocalin 2 was detected after 5 h in CSF during experimental infection in mice." (PMID 24885531, 2014). "Interestingly, one of these proteins, LCN2, was overexpressed in the brain of infected mice after 6 h of infection." (PMID 24885531, 2014). "Mice expressing Lcn2 are more resistant to infections with such Gram-negative bacteria as compared to Lcn2-/- littermates which is cause-effectively due to the bacterial iron withholding capacity of Lcn2." (PMID 25076907, 2014). "We first explored whether lipocalin 2 was detectable in CSF from infected mice during experimental infection as expected from the previously reported overexpression of lipocalin 2 specific transcripts in brain." (PMID 24885531, 2014). "Moreover, colonic expression of MMP-2 and TIMP-1 was similar in Lcn2+/+ and Lcn2−/− mice after infection, excluding their involvement in this process." (PMID 24465207, 2014). "For example, Ido1 has anti-microbial activity in a variety of infectious diseases, and LCN2 has been reported to be as a bacteriostatic protein for protection of airways against infection by E. coli; 3) Components response to cytokines and reactive oxygen species were significantly modulated." (PMID 23826353, 2013). "Furthermore, the application of recombinant Lcn2 as a therapeutic agent can be one of the potential solutions for some diseases such as ischemic renal injury and infection." (PMID 23493520, 2012). "In summary, we project a new role for Lcn2 in pulmonary infections where apart from its role in sequestering iron and inhibiting growth of bacteria, infection-induced Lcn2 can also act on mucosal cells to regulate chemokines such as CXCL9 and restrain inflammation at mucosal sites." (PMID 23185529, 2012). "Lipocalin 2 (LCN2) is known to be highly up-regulated in skin injury and infection events." (PMID 23285167, 2012). "This creates a role for Lcn2 in tissue-protection against infection." (PMID 23493520, 2012). "Lcn2 is induced early in the lung in response to M.bovis BCG infection from day 2 post infection." (PMID 23185529, 2012). "Lipocalin 2 is important for protection of airways against infection by E. coli." (PMID 20633248, 2010). "When testing a mutated form of K. Pneumonia that was unable to synthesize Ybt as well as glycosylate enterobactin, wildtype mice were able to combat infection with this bacterium whereas lipocalin 2 deficient mice were not." (PMID 20633248, 2010). "In addition, a higher number of E. coli was found in the spleen of surviving lipocalin 2 knock-out mice on day 5 post-infection than in the corresponding wild-type mice (p < 0.05)." (PMID 20633248, 2010).
infection (continued). "Our data demonstrate that lipocalin 2 is important for hindering infection of the lungs by E. coli." (PMID 20633248, 2010). "Whereas the ability of Lcn2 to sequester iron is well described, the ability of Lcn2 to induce inflammation during infection is unknown." (PMID 19834550, 2009). "For instance, Lcn2 plays an important role in iron acquisition during infection." (PMID 17375196, 2007). "These proteins have defined roles in fungal virulence, supporting their detection within the infection model and the abundance changes correlate with a limited host immune response where only immunoglobulin activation is observed, along with low levels of lipocalin-2." (PMID 41061967, 2025). "In addition to CD11b, several proteins are known to be strongly expressed by neutrophils, such as myeloperoxidase (MPO), the antimicrobial protein lipocalin (LCN2), neutrophil gelatinase-associated lipocalin (NGAL), and neutrophil elastase (ELANE), were strongly enriched in AM upon infection." (PMID 37790937, 2023). "Moreover, lipocalin-2 can bind to iron with a much higher affinity than the endogenous carrier protein transferrin, thus potentially aiding pathogen survival and growth during infection." (PMID 37629516, 2023). "Thus, the increase in AQP4, combined with increased LCN2 expression, might be an underlying event associated with the BBB dysfunction in our mouse model of infection." (PMID 37496672, 2023). "Also, both strains elicited gut inflammation within the first 3 days of infection, as assessed by ELISA for the gut inflammation marker lipocalin-2 (left side), which is expressed by the infected mucosa and provides a reasonable assay for probing the time course of gut inflammation." (PMID 37651408, 2023). "Accordingly, the expression of LCN2 in the central nervous system not only is important in the early stages of SCI, but also may affect the risk of adverse outcome and the quality of life in patients with SCI, especially those who encounter an infection." (PMID 37240031, 2023). "In addition, Lcn2 may be important for host defense against a wider variety of extracellular microorganisms because it attracts neutrophils to the site of infection." (PMID 37946846, 2023). "In further refining our understanding of the role of LCN2 in infection, not only should inocula of varying concentrations be used, but studies should be extended beyond A. baumannii ATCC 17978 to validate hypotheses using more modern clinical isolates, as well as to additional lineages of mice." (PMID 36054235, 2022). "Given that LCN2 plays a wide role in preventing infection and sterile inflammation in various animal models, LCN2-mediated ferroptosis resistance may be a common mechanism driving cell protection and reducing morbidity and mortality, a possibility that awaits further investigation in future studies." (PMID 33510144, 2021). "Thus, we speculate that Lcn10, like Lcn2, might be stimulated by inflammation or infection playing a role in the regulation of acute cardiac injury." (PMID 34121925, 2021). "Lipocalin-2 (LCN2), also known as neutrophil gelatinase-associated lipocalin (NGAL), is released by various cell types that has been found to be involved in multiple processes such as metabolic homeostasis, apoptosis, infection, immune response, or inflammation." (PMID 32605546, 2020). "Although Lcn2 secretion and its concentrations are low in normal physiological conditions, brain injury or infection could promote Lcn2 secretion and increased expression of cationic Lcn2 receptor (24p3R) in astrocytes, activated microglia, and endothelial cells in CNS." (PMID 32622362, 2020). "Our observation of apparent highest lipocalin-2 expression in EM-MSCs may be linked to the fact that, unlike BM or AT, EM provides a natural body barrier against infection." (PMID 30044182, 2018).
infection (continued). "Lipocalin-2 has previously been proposed to play a role in iron homeostasis and we speculated whether the growth-promoting effect of lipocalin-2 at 3 weeks after infections was related to changes in iron metabolism." (PMID 30534124, 2018). "To determine whether the regulation of PPARγby S. Typhimurium is a transient effect or whether the Lcn2−/− mice are protected at later stages of infection, we infected PPARγVillinCre-, PPARγVillinCre+, Lcn2−/−, and Lcn2+/+ mice with S. Typhimurium and sacrificed them after 72 h." (PMID 24465207, 2014). "We therefore decided to investigate whether lipocalin 2 has a role in protection against E. coli when these are introduced in the airways and need to overcome the protection provided by the epithelial lining in order to establish infection." (PMID 20633248, 2010). "Furthermore, lipocalin 2 is stored in the specific granules of neutrophils from which it may be exocytosed when these cells have migrated to a site of infection." (PMID 20633248, 2010). "In order to further clarify the mechanism of Lcn2 production, macrophages were pretreated with 2 μmol/L MCC950 before infection with the P7 strain." (PMID 39180285, 2025). "A direct correlation between fecal shedding, fecal LCN2 levels and CCH was observed following infection with the CRi17 and CRP20 intermediates." (PMID 40599135, 2025). "Expression of Lcn2, encoding the proinflammatory marker lipocalin-2, was significantly elevated in mRNA isolated from preparations of ileal epithelial cells starting at 3 d after infection with the S. Typhimurium WT, but not after infection with the avirulent invA spiB mutant." (PMID 39546570, 2024). "In neutrophils, LCN2 secretion is highly stimulated by inflammation and infection activation, and LPS and TNF‐α are two potent inducers of LCN2 production." (PMID 37060578, 2023). "Expression of other genes that were strongly upregulated after infection with most mycobacteria included SERPINB1, CXCL2, CXCL8, CXCL10, and LCN2." (PMID 37822359, 2023). "Lipocalin-2 (LCN2) plays a central role in protecting and regulating against intracellular infection by scavenging iron." (PMID 37942316, 2023). "Lipocalin-2 (LCN2) is an acute-phase protein produced in response to injury, infection, or other inflammatory conditions." (PMID 35281301, 2022). "Animals with BRD show decreased expression of genes for hemoglobin and iron-binding proteins and regulators and an increase in genes for iron maintenance proteins (i.e., LCN2 and LTF) that are released from neutrophils as a response to infection." (PMID 33763112, 2021). "Lipocalin-2 (LCN-2) in the liver shows a protective role against pernicious conditions, such as infection, inflammation, and other forms of cellular stress." (PMID 34684425, 2021). "To establish the effect of LCN2 on the regulation of intracellular survival of Mtb in an in vivo system, we measured intracellular Mtb by CFU counts in the lungs at 10 days post-infection." (PMID 34563261, 2021). "Our findings demonstrate that NF-κB/LCN2 is necessary for migration and phagocytosis of M1 macrophages in response to SWA infection." (PMID 34616693, 2021). "In fact, host defense (antimicrobial) peptides such as CATHL6, LCN2, and PGLYRP-1 are attractive candidates for therapeutic development and represent potential alternatives to antimicrobials for infection management." (PMID 33195534, 2020). "Fe-supplementation resulted in a significant down-regulation of HFE3 (TFR2), HAMP, FPN1, and LCN2 while BMP6 and FTH1 were significantly up-regulated, compared to the placebo group, at 4 weeks post-infection." (PMID 31382404, 2019). "The protective role of lipocalin-2 (NGAL/Lpc-2), produced by innate immune cells at an early stage of infection, is well known." (PMID 31183362, 2019).
infection (continued). "At 8 weeks post-infection, expression of BMP6, HAMP, FPN1, FTH1, NRF2, and LCN2 was significantly up-regulated, while HFE1 was significantly down-regulated by Fe-supplementation, compared to the placebo group." (PMID 31382404, 2019). "To our surprise we observed a nearly 2-fold higher infection burden (CFU, colony-forming units) in lungs of WT mice 3 weeks post-challenge compared to mice unable to produce lipocalin-2." (PMID 30534124, 2018). "Furthermore, we wanted to elucidate whether the cellular origin of lipocalin-2 is important for infection control by establishing a chimeric bone marrow model that would allow us to discriminate myeloid cell-derived lipocalin-2 from epithelia cell-derived lipocalin-2." (PMID 30534124, 2018). "We also examined the localization of Lcn2 and LC3 in macrophages after infection with E. coli by immunocytochemistry." (PMID 27734904, 2016). "Our data suggests a model whereby the pathogenesis of S. Typhimurium involves manipulation of the host innate immune and protease system, here illustrated by PPARγ, Lcn2 and MMP-9, to establish colonization and infection within the host." (PMID 24465207, 2014). "Results from the microarray validated by Q-RT-PCR, and in selected cases at the protein level, indicate a down-regulation of genes such as C1S, LCN2 and PI3 after infection with N. meningitidis relative to N. lactamica." (PMID 22028815, 2011). "However, PMNs infiltrating the brain of Rag1–/– mice exhibited a mix of proinflammatory (LCN2, APOE) and antiinflammatory (WFDC21, RETNLG) molecules that was most prominent at day 7 after infection along with enhanced PD-1/PD-L1 pathway expression." (PMID 39989461, 2025). "However, the host can prevent iron uptake by pathogenic bacteria by releasing lactoferrin (chelating Fe3+), lipocalin-2 (LCN2) (sequestering siderophores), and calprotectin (CP) (sequestering Fe2+) from neutrophils or IECs at the sites of infection." (PMID 39341502, 2024). "This study found that mice lacking Lcn2 exhibited more severe pulmonary pathological damage following infection with M. bovis." (PMID 39051782, 2024). "Furthermore, Cxcr2 expression in tissues associated with sterile implants was unchanged in mice receiving any dose of Lcn2, revealing that recruitment of CXCR2-expressing cells was dependent on infection." (PMID 38567642, 2024). "To further assess the immunological response to infection with and without Lcn2 treatment, we first quantified tissuecombat their antimicro levels of IL-10, an important determinant of S. aureus implant infection outcomes." (PMID 38567642, 2024). "Lipocalin 2, a marker of oxidative stress, was also elevated with ethanol consumption, though not with infection." (PMID 39767664, 2024). "In contrast, only an infection-induced increase in lipocalin-2, but not lactoferrin, was observed in the plasma of infected mice." (PMID 37669943, 2023). "Lipocalin (LCN)-2 (NGAL) was not significantly altered in severe infection (p = 0.77) but was significantly decreased in the moderate infection group (p = 0.001)." (PMID 37598150, 2023). "Activation of astrocytes is expected to occur in the presence of WNV, and this was observed in the BSCs following WNV infection because GFAP, VIM, LCN2, and STEAP4 all showed enhanced expression following infection with WNV compared with the mock-infected samples." (PMID 35412380, 2022). "Given the homology between LCN2, LCN12, and other lipocalin family proteins, one or more of the homologous proteins are likely binding to the polyclonal antibody and are targets that are also upregulated during infection." (PMID 36054235, 2022). "Moreover, LCN2/PEPCK/TNFR2 and LIF/FOS showed almost constant up- and down-regulated expression, respectively, across all three infection time-points studied in both groups." (PMID 35234615, 2022).